LIN28B (lin-28 RNA binding posttranscriptional regulator B)
Diseases named in the same sentence as LIN28B in open-access papers (continued):
Sharing a sentence is not in itself a finding about the gene and the disease.
pancreatic cancer (24 papers, 2013 to 2025). "The mechanism through which Lin28B in exosomes activates the Lin28B/let-7/HMGA2/PDGFB signaling pathway in recipient pancreatic cancer cells." (PMID 38954230, 2024). "Here in our study, we found that a positive feedback loop between Wnt5a and Lin28b in pancreatic cancer cells." (PMID 37898598, 2023). "have demonstrated that, the nuclear translocation of Lin28B, highly expressed in pancreatic cancer tissues, is promoted by KRAS through protein kinase C (PKCβ)." (PMID 35651786, 2022). "For example, in recent studies, circulating tumor cells (CTC)-iChip technology is applied to purify CTC from pancreatic cancer patients for RNA-seq characterization, displaying the enrichment of main relevant genes in the stem genes LIN28B/KLF4." (PMID 35027543, 2022). "Our results suggest that the KRAS/Lin28B axis drives the let‐7i/TET3 pathway to maintain the stemness of pancreatic cancer cells." (PMID 33107691, 2021). "In the present context, SIRT6 protein acts as a suppressor of colon tumorigenesis, which suppresses pancreatic cancer through control of the zinc finger protein Lin28b, which drives the growth and survival of SIRT6-deficient pancreatic cancer." (PMID 33510943, 2021). "Firstly, we observed that Lin28B was upregulated in pancreatic cancer, contributing to cellular migration and proliferation." (PMID 33107691, 2021). "In pancreatic cancer, K-Ras blocks let-7i maturation by phosphorylating Lin28B at S243 and promoting Lin28B nuclear translocation." (PMID 34572067, 2021). "To further determine the role of Lin28B in PC, we examined the effect of Lin28B on pancreatic cancer cell migration by wound healing assays." (PMID 33107691, 2021). "Compared with the adjacent normal tissues, Lin28B expression was significantly higher in pancreatic cancer tissues." (PMID 33107691, 2021). "Since the Lin28B levels were significantly correlated with lymph node status and distant metastases in the PDAC samples, we examined the role of Lin28B in pancreatic cancer cell migration." (PMID 28947981, 2017). "Lin28B overexpression dramatically accelerated the transitions through the cell cycle and increased pancreatic cancer cell colony formation and migration." (PMID 28947981, 2017). "Lin28B was ectopically expressed via a lentiviral infection system to establish stable BxPC-3 pancreatic cancer cells which normally express low levels of Lin28B, to determine the effect of Lin28B overexpression." (PMID 28947981, 2017). "Lin28B was markedly upregulated in pancreatic cancer tissues but was nearly undetectable in normal pancreatic tissues." (PMID 28947981, 2017). "In pancreatic cancer, the protein Lin28B in cancer cell-derived exosomes is transformed into these neighbor cancer cells to activate the Lin28B/let-7/HMGA2/PDGFB signaling pathway, promoting interaction with PSCs to enhance their migration to micro-metastatic sites." (PMID 37173915, 2023). "Thus, our study shows that the Lin28b-Wnt5a axis plays a critical role in bidirectional crosstalk between pancreatic tumor epithelium and TME and results in a pro-‍tumorigenic contexture." (PMID 37898598, 2023). "The increased TET3 will activate Lin28B for maintaining the stemness of pancreatic cancer." (PMID 35651786, 2022). "Thus, KRAS maintains the stemness of pancreatic cancer cells through a unique Lin28B/let-7i/TET3 feedback loop." (PMID 35651786, 2022). "To determine whether Lin28B is involved in pancreatic cancer progression, we first analyzed Lin28B messenger RNA (mRNA) levels in 14 pairs of PC tissues and paired adjacent normal tissues." (PMID 33107691, 2021). "However, the molecular mechanism of Lin28B nuclear translocation and its role in the development and progression of pancreatic cancer remained unclear." (PMID 33107691, 2021). "However, the molecular mechanism of Lin28B nuclear translocation and its roles in the development and progression of pancreatic cancer remain poorly understood." (PMID 33107691, 2021).
pancreatic cancer (continued). "It is suggested that Lin28B plays a key role in KRAS‐driven pancreatic cancer." (PMID 33107691, 2021). "The KRAS/Lin28B axis maintains stemness of pancreatic cancer cells via the let‐7i/TET3 pathway." (PMID 33107691, 2021). "The group showed that pancreatic cancer cell-derived exosomes containing Lin28B (Exo-Pan and Exo-Mia) promoted the recruitment of PSCs by activating the Lin28B/let-7/HMGA2/PDGFB signaling pathway, which highlights the importance of exosomal signaling in cancer." (PMID 34646829, 2021). "In conclusion, pancreatic cancer cell-derived exosomes could transfer the exosomal protein Lin28B to pancreatic cancer cells, thus facilitating their recruitment of PSCs via the Lin28B/let-7/HMGA2/PDGFB pathway." (PMID 31413760, 2019). "Lin28B was silenced using a lentiviral infection system to establish two stable pancreatic cancer cell lines, AsPC-1 and Hs766t, both of which express high levels of Lin28B, to investigate whether Lin28B plays a role in the pathogenesis of PDAC." (PMID 28947981, 2017). "Immunohistochemistry was performed for serial sections of pancreatic tumor tissue from the KPC orthotopic transplantation model with antibodies to E2F2, H3S28ph, LIN28B, and other markers whose gene expression was suppressed by BA in vitro." (PMID 40316727, 2025). "LINC01094 regulates lin-28 homolog B (LIN28B) expression and PI3K/AKT pathway serving as a ceRNA of miR-577, which promotes the proliferation and metastasis of pancreatic cancer." (PMID 36824662, 2023). "They found that KRAS promoted the nuclear translocation of LIN28B and that the KRAS/Lin28B axis drove the let-7i/TET3 pathway to maintain the stem-cell like phenotype of pancreatic cancer cells." (PMID 37304235, 2023). "Upregulated KRAS promotes Lin28B nuclear translocation by PKCβ, but nuclear Lin28B further represses the production of let‐7, forming a KRAS/Lin28B/let‐7 loop in pancreatic cancer." (PMID 33107691, 2021). "In this study, we found that Lin28B was significantly more highly expressed in pancreatic cancer tissues than in the pancreatic cancer adjacent tissues, and showed that KRAS promoted the nuclear translocation of Lin28B by protein kinase C (PKCβ)." (PMID 33107691, 2021). "This study elucidates the distinct mechanism of Lin28B nuclear translocation, and illustrates a new pathway of KRAS‐driven pancreatic cancer." (PMID 33107691, 2021). "Therefore, our results illuminate the distinct mechanism of Lin28B nuclear translocation and suggest that the KRAS/Lin28B axis drives the let‐7i/TET3 pathway to maintain the stemness of pancreatic cancer cells." (PMID 33107691, 2021). "In this study, we find that LIN28A increases the expression of stem cell markers SOX2, OCT4, LIN28B, c-Myc and NANOG in pancreatic cancer cells, and promotes their malignant behaviors including growth and invasion in vitro, further supporting the oncogenic potential of LIN28A." (PMID 26910839, 2016). "There are several specific exosomes that can contribute to liver metastasis in pancreatic cancer via forming an inflammatory and immunosuppressive microenvironment in the liver, e.g., macrophage migration inhibitory factor (MIF), Integrin ITG αvβ5, Netrin-1, Lin28B and CD44." (PMID 38954230, 2024).
colon carcinoma (21 papers, 2011 to 2023). "LIN28B is associated with aggressive subtypes in certain cancers including high-grade serous ovarian cancers, esophageal cancer and colon cancer." (PMID 32571380, 2020). "Since the expression of both Lin28A and Lin28B is associated with colon cancer metastasis, we evaluated and compared the influence of both onco-proteins on the migration and invasion of HCT116 cells in vitro." (PMID 27793004, 2016). "Here, we have also confirmed the overexpression of Lin28B in colon cancer, and have showed that Lin28B expression is associated with lymph node metastasis of colon cancer, which is consistent with previous researches." (PMID 27793004, 2016). "In conclusion, LIN28B overexpression contributes to colon tumourigenesis, and LIN28B may serve as a diagnostic tool and therapeutic target for colon cancer." (PMID 25360631, 2014). "LIN28B is another transcription factor highly expressed in colon cancer; researchers found that this protein had great effects on the dedifferentiation of colon cancer cells." (PMID 34976166, 2022). "We have demonstrated that LIN28B overexpression correlates with poor survival in colon cancers and increased tumor recurrence." (PMID 33755595, 2021). "LIN28B-overexpressing colon cancer cell lines that result in xenograft tumors are more glandular and differentiated compared with xenograft tumors generated from empty vector cell lines." (PMID 33755595, 2021). "Yuan and Tian demonstrated that overexpression of LIN28B increases B-cell lymphoma 2 expression to promote colon cancer development." (PMID 34497681, 2021). "LIN28B overexpression is related to reduced patient survival and increased probability of tumor recurrence in colon cancers." (PMID 32571380, 2020). "For instance, LIN28B overexpression promoted tumorigenesis and metastasis of colon cancer via repressing the level of let-7 microRNAs." (PMID 32983230, 2020). "LIN28B enhances cell migration, invasion and metastasis in some cancers such as prostate cancer and colon cancer." (PMID 32571380, 2020). "Consistent with our findings, TRIM71 has also been shown to have a tumor suppressive role in lung and colon cancer cells by mediating degradation of LIN28B and consequently upregulating the tumor suppressive microRNA let-738,39." (PMID 31570706, 2019). "Lin28B overexpression correlates with reduced patient survival and promotes colon cancer metastasis and recurrence." (PMID 28947981, 2017). "For example, Lin28B is overexpressed in stage I and II colon cancers and correlates with reduced survival and an increased probability of tumor recurrence." (PMID 28947981, 2017). "One of recent report has shown that Lin28B promotes migration, invasion, and transformation by associating and repressing LGR5 and PROM1 mRNAs that are essential for colon cancer progression." (PMID 27821801, 2016). "Analyzing together, we demonstrated that Lin28B is predominantly located in the cytoplasm of colon cancer cells, which is contradictory to the previous report." (PMID 27793004, 2016). "In this study, we have confidently demonstrated that Lin28B is majorly expressed in the cytoplasm instead of the nucleus in colon cancer cells." (PMID 27793004, 2016). "The mRNA expression of both Lin28A and Lin28B was also analyzed in 162 colon cancer patients, and the results showed that the mRNA level of Lin28B is also significantly higher than mRNA level of Lin28A in colon cancer (P<0.01)." (PMID 27793004, 2016). "Successively, several other studies also provided evidence for the involvement of Lin28B in colon cancer development and progression." (PMID 27793004, 2016). "To learn the expression pattern of Lin28A and Lin28B in colon cancer, we initially detected the expression of both oncogenic proteins in 65 colon cancer tissues and 10 normal tissues using immunohistochemistry staining." (PMID 27793004, 2016).
colon carcinoma (continued). "The results showed that Lin28B protein is expressed in all the observed colon cancer tissues samples (positive rate is 100%), whereas Lin28A protein is expressed in 57 out of 65 samples (positive rate is 87.7%)." (PMID 27793004, 2016). "To examine the potential roles for LIN28B in colon cancer, we first compared LIN28B protein expression between 208 tumour samples and 8 non-matched normal mucosa samples from a tissue microarray using IHC." (PMID 25360631, 2014). "LIN28B was upregulated in colon cancer tissue compared to normal mucosa, and its overexpression correlated with reduced patient survival and increased tumour recurrence." (PMID 25360631, 2014). "Taken together, our results reveal that LIN28B expression is closely related to overall patient survival and recurrence of colon cancer." (PMID 25360631, 2014). "Because Let-7 functions as a potential growth suppressor in human colon cancer cells, we examined LIN28B expression in colon cancer tissues to determine the balance between LIN28B and let-7 expression." (PMID 25360631, 2014). "LIN28B suppression inhibited the migration of SW480 colon cancer cells and facilitated the cytotoxicity induced by oxaliplatin in SW480 and HCT116 colon cancer cells." (PMID 25360631, 2014). "We found that LIN28B expression was upregulated in colon tumour tissues, and this expression correlated with reduced patient survival, and a higher probability of recurrence." (PMID 25360631, 2014). "We examined LIN28B expression in human colon cancer tumours via tissue microarray and found that LIN28B was significantly upregulated in tumour tissue compared to normal colonic mucosa." (PMID 25360631, 2014). "Loss-of-function, migration and proliferation analyses were performed to delineate the potential roles of LIN28B in colon cancer." (PMID 25360631, 2014). "In another recent report, high Lin28B staining intensity in stage I/II colon cancers correlated with reduced survival and increased probability of tumour recurrence." (PMID 22433967, 2012). "In addition, LIN28B promotes the proliferation, colony formation and tumourigenesis of colon cancer cells by increasing BCL-2 expression." (PMID 32828126, 2020). "Although the LIN28B overexpression in colon cancer has been linked to colon cancer progression, the molecular pathways connecting LIN28B and other proteins directly involved in invasion have not been identified." (PMID 31692974, 2019). "However, the expression of Lin28B in all of the observed colon cancer tissues is also predominantly localized in the cytoplasm instead of the nuclei, which is different from the previous observation." (PMID 27793004, 2016). "In this study, we have systematically evaluated the expressional pattern and correlation of both Lin28A and Lin28B in colon cancer tissues, and have determined and compared the roles of Lin28A and Lin28B in the proliferation, migration, invasion and apoptosis of colon cancer cells in vitro." (PMID 27793004, 2016). "Consistently, our result of cell migration and invasion also demonstrated that both of Lin28A and Lin28B could promote the migration and invasion of colon cancer cells in vitro." (PMID 27793004, 2016). "For instance, several studies showed that Lin28B is overexpressed in colon cancer and promotes colon cancer progression, whereas the expression and functions of Lin28A in colon cancer are largely unknown." (PMID 27793004, 2016). "In this study, we have evaluated the co-expression of Lin28A and Lin28B in colon cancer tissues for the first time, and we showed that both oncogenes are expressed in colon cancer tissues, and the expression of Lin28B was significantly higher than the expression of Lin28A." (PMID 27793004, 2016). "And the result showed that the expression of neither Lin28A nor Lin28B is significantly associated with the prognosis of colon cancer patients." (PMID 27793004, 2016).
colon carcinoma (continued). "LIN28B protein was found to be unregulated in colon tumours, and the overexpression correlated with reduced patient survival and increased probability of tumour recurrence 34, 37; besides, LIN28B can promote migration, invasion, and malignant transformation of cells." (PMID 27021521, 2016). "Additionally, the mRNA level of Lin28A instead of Lin28B in colon cancer patients with remote organ metastasis is significantly higher than that of patients with non-metastasis." (PMID 27793004, 2016). "Further, we detected the subcellular distribution of Lin28B protein in colon cancer cell lines." (PMID 27793004, 2016). "As LIN28B overexpression was correlated with tumour recurrence and patient survival, we next sought to explore whether LIN28B expression influences the migration of colon cancer cells." (PMID 25360631, 2014). "We examined LIN28B expression in three colon cancer cell lines using RT-PCR and Western blotting." (PMID 25360631, 2014). "The results indicated a synergistic effect between si-LIN28B and oxaliplatin, which suggests that the targeting of LIN28B may be capable of sensitising colon cancer cells to oxaliplatin therapy." (PMID 25360631, 2014). "MYCN amplification also results in LIN28B overexpression, and it has been reported that c-Myc is related to sporadic large bowel cancer and familial polyposis coli, implying a role for LIN28B in colon cancer." (PMID 25360631, 2014). "Additionally, the silencing of LIN28B sensitised colon cancer cells to cytotoxicity induced by oxaliplatin and inhibited their migration in vitro." (PMID 25360631, 2014). "In this study, we showed that LIN28B expression promotes migration and recurrence of colon cancer." (PMID 25360631, 2014). "LIN28B overexpression is known to contribute to carcinogenesis by blocking the biogenesis of let-7, which prompted us to evaluate whether the balance between tumour-promoting LIN28B and tumour-suppressive let-7 was altered in colon cancer." (PMID 25360631, 2014). "LIN28B may be overexpressed in some tumors such as colon cancer." (PMID 32571380, 2020). "Additionally, although the expression and role of Lin28B in colon cancer is frequently reported, the expression and functions of Lin28A in colon cancer are largely unknown." (PMID 27793004, 2016). "Increased Lin28B expression is correlated with a poor prognosis in patients with HCC, colon cancer, gastric cancer and esophageal cancer." (PMID 28947981, 2017). "For colon cancer, we performed immunohistochemistry on 45 human tumor samples where 19 were LIN28A-positive while 14 expressed LIN28B." (PMID 28400788, 2017). "Lin28B overexpression is observed in hepatocellular cancer (HCC), breast cancer, lung cancer, colon cancer, esophageal cancer, melanoma, gastric cancer and oral squamous cell carcinoma (OSCC)." (PMID 28947981, 2017). "Furthermore, we found that silencing LIN28B inhibited the migration of SW480 cells and sensitised SW480 and HCT116 colon cancer cells to oxaliplatin-induced cytotoxicity." (PMID 25360631, 2014). "In contrast to embryonic stem cells, where let7 and LIN28 co-regulate each others' expression, let7 fails to inhibit the effects of LIN28B, suggesting that LIN28B can act independently of Let7 in this colon cancer model." (PMID 24213119, 2011).